ENSG00000201467
Synonyms: LOC124905266
Gene: Small nucleolar RNA gene on chromosome X (17,044,380 to 17,044,511, reverse strand). Ensembl gene ENSG00000201467.
Gene Ontology:
Biological process: RNA processing
Cellular component: nucleolus
Homologues: Orthologues: rat LOC120099445 (77% identical), mouse Gm23454 (74% identical). Paralogues in human: SNORA16A (86% identical), SNORA16B (81% identical).